LTF (lactotransferrin)
Diseases named in the same sentence as LTF in open-access papers (continued):
Sharing a sentence is not in itself a finding about the gene and the disease.
prostate carcinoma (15 papers, 2008 to 2026). A carcinoma that arises from epithelial cells of the prostate gland. "Overexpression of LTF resulted in a significant increase in lipid reactive oxygen species (LipROS), a hallmark of ferroptosis, in prostate cancer cells." (PMID 40082405, 2025). "LTF is deficient or lowly expressed in prostate cancer, nasopharyngeal carcinoma, oral squamous cell carcinoma, etc.." (PMID 35096061, 2022). "LTF mRNA and protein levels are downregulated in prostate cancer, with significant PSA recurrence associations, due to promoter silencing by hypermethylation." (PMID 19055846, 2008). "LTF has been found to be down-regulated in papillary thyroid cancer, gastric cancer, and underexpressed in association with hypermethylation in prostate cancer and nasopharyngeal carcinoma, supporting a role as a tumor suppressor gene in a variety of cancer types." (PMID 32366326, 2020). "High LTF expression corresponded with increased pathway enrichment scores, suggesting a key role for LTF in promoting ferroptosis in prostate cancer cells." (PMID 40082405, 2025). "The tumor-suppressive effects of LTFe are primarily mediated through LTF activation, underscoring the therapeutic potential of targeting the LTFe-LTF axis in prostate cancer treatment." (PMID 40082405, 2025). "Collectively, this study provides novel insights into the mechanistic role of eRNAs in prostate cancer, highlighting the LTFe-LTF axis as a critical epigenetic regulator and potential therapeutic target for improved treatment outcomes." (PMID 40082405, 2025). "Functional assays revealed that LTFe inhibits prostate cancer cell proliferation and enhances ferroptosis, a form of iron-dependent cell death, by regulating the expression of its downstream target gene, lactotransferrin (LTF)." (PMID 40082405, 2025). "Our findings suggest that LTFe exerts tumor-suppressive effects by modulating chromatin architecture, leading to the transcriptional activation of LTF, which in turn inhibits prostate cancer proliferation in both in vitro and in vivo models." (PMID 40082405, 2025). "Among the candidates, lactotransferrin-eRNA (LTFe) emerged as a key tumor suppressive eRNA, exhibiting significantly reduced expression in prostate cancer tissues compared to normal controls." (PMID 40082405, 2025). "Together, these results provide compelling evidence that LTF plays a pivotal role in suppressing prostate cancer proliferation." (PMID 40082405, 2025). "Among these, lactotransferrin-eRNA (LTFe) was markedly downregulated in prostate cancer tissues, with functional analyses revealing its tumor-suppressive role." (PMID 40082405, 2025). "A lower expression of LTF has been shown in tumours such as prostate cancer (CaP), NPC, osteosarcoma, clear cell renal cell carcinoma (ccRCC) and OSCC." (PMID 36360322, 2022). "Studies in nasopharyngeal carcinoma and prostate cancer suggested a tumor suppressor function for LTF." (PMID 36153549, 2022). "One study identified LTF as the most significantly down-regulated gene in prostate cancer cells and proved that LTF protein can inhibit the growth of prostate cancer cells." (PMID 30367578, 2018). "Another gene classified as one of the most discriminative prostate cancer biomarkers, whose anti-tumorigenic role has already been described is lactotransferrin (LTF)." (PMID 19055846, 2008). "Low expression of LTF can promote the proliferation of prostate cancer." (PMID 38763993, 2024). "Recently, several studies have reported that LTF was downregulated and may act as a tumor suppressor in several types of cancer such as prostate cancer, clear cell renal cell carcinoma, oral squamous cell carcinoma and nasopharyngeal carcinoma." (PMID 38763993, 2024). "In addition, the potent tumor suppressor role of LTF has been shown in hepatic steatosis and several human cancers, including nasopharyngeal carcinoma, prostate cancer, and clear cell renal cell carcinoma." (PMID 37016705, 2023).
prostate carcinoma (continued). "The LTF promoter hypermethylation was also reported in prostate cancer." (PMID 36551770, 2022). "Qi Zhao found LTF could regulate the immune microenvironment of prostate cancer through JAK/STAT3 Pathway." (PMID 36064366, 2022). "Moreover, through hypermethylation, LTF silencing during the development of prostate cancer supports the role of LTF as a tumor suppressor gene." (PMID 34266418, 2021). "Five of these top seven genes namely, MYLK, KLK2, KLK3, LTF and TGM4 had already been specifically related to prostate carcinoma." (PMID 19055846, 2008). "Additionally, LTF expression was markedly lower in prostate cancer tissues compared to adjacent non-cancerous tissues." (PMID 40082405, 2025). "The MYLK, KLK2, KLK3, HAN11, LTF, CSRP1 and TGM4 genes presented significant changes in their functional connectivity between normal and tumoral conditions and were also classified as the top seven most informative genes for the prostate cancer genesis process by our discriminant analysis." (PMID 19055846, 2008). "While we did not detect a separate hillock cell population within our prostate cancer epithelial cells, we did detect a distinct population representing 6.5% of all epithelial cells (872 of 13,322) characterized by expression of PIGR, MMP7, CP, and LTF (FDR q < 10e-20)." (PMID 35013146, 2022).
COVID-19 (13 papers, 2022 to 2025). A disease caused by infection with severe acute respiratory syndrome coronavirus 2. "Based on the Degree, MCC, Closeness, Betweenness, and MNC algorithms of the CytoHubba plug-in, six genes (FPR1, FCGR2A, TLR4, S100A12, CXCL1, and LTF) were confirmed as hub genes related to COVID-19 severe." (PMID 38674681, 2024). "As the major components in milk, the two most abundant glycoproteins, lactoferrin (LTF) and sIgA1, exhibited different glycosylation pattern alteration trends in response to COVID-19." (PMID 35745243, 2022). "We performed a study using peripheral blood mRNA-seq data from 41 COVID-19 patients to obtain the immune-characterized genes of COVID-19 severe disease, namely, the hub genes (FPR1, FCGR2A, TLR4, S100A12, CXCL1, and LTF)." (PMID 38674681, 2024). "The COVID-19 dataset revealed CAMP (AUC: 0.692), LTF (AUC: 0.764), DEFA1B (AUC: 0.701), SAMD9(AUC: 0.786), GBP1(AUC: 0.757), DDX60 (AUC: 0.802), DEFA4 (AUC: 0.763), and OAS3(AUC: 0.801) that exhibited superior diagnostic capabilities." (PMID 38115996, 2023). "Genes associated with the immature neutrophil subset (CD24, LTF, CAMP) were up-regulated in COVID-19(+) TV skin, but not in COVID-19(+) PU or COVID-19(-) PU skin tissue." (PMID 37026002, 2023). "When the blood transcriptomic profiles of patients with mild COVID-19 were compared with the profiles from patients with moderate or severe COVID-19, CEACAM8, MMP8, ELANE, LTF, CEACAM6 and MPO were consistently amongst the top SDE genes, with levels increasing with severity and high LFCs." (PMID 35844004, 2022).
nasopharyngeal carcinoma (13 papers, 2014 to 2024). A carcinoma arising from the nasopharyngeal epithelium. "The lactoferrin (LTF) gene behaves like a tumor suppressor gene in diverse tumors, such as renal cancer, nasopharyngeal carcinoma and gastric cancer." (PMID 38763993, 2024). "LTF has also been suggested to downregulate the development of nasopharyngeal carcinoma by inhibiting the proliferation through induction of cell cycle arrest and modulation of the MAPK signaling pathway." (PMID 37056929, 2023). "Lactotransferrin is an iron-binding protein that regulates the binding and transport of ferric ions; moreover, it can suppress nasopharyngeal carcinoma, besides its role in innate immunity." (PMID 35268677, 2022). "Downregulation of LTF can be found in multiple cancers, including triple-negative breast cancer, nasopharyngeal carcinoma, and renal clear cell carcinoma." (PMID 34266418, 2021). "Yi HM and others discovered expression, genetic and epigenetic alterations of the LTF gene in nasopharyngeal carcinoma cell lines." (PMID 33585219, 2020). "Additionally, this miRNA can regulate the ferroptosis of nasopharyngeal carcinoma cells by regulating lactotransferrin (LTF)." (PMID 38313306, 2024). "Another study demonstrated that LTF expression was negatively correlated with metastases and T-stage in nasopharyngeal carcinoma (NPC) samples." (PMID 36551770, 2022).
viral infection (13 papers, 2011 to 2024). "For example, over half of these genes have been previously associated with viral infection or replication, or have been found to physically interact with viral proteins (e.g. CLDN3; CRHR2; ILF2; ILF3; LTF; miR-122; RCHY1; and, RUVBL2)." (PMID 25079789, 2014). "Additionally, we also observed that some genes, such as LCN2 and LTF were predicted to be involved in the cell-mediated immune response, indicating they may be key genes to against viral infections." (PMID 36579334, 2022). "Targeted analysis of MMP9 (matrix metallopeptidase 9), PADI4 (peptidyl arginine deiminase 4) and LTF (lactotransferrin) showed these to be elevated in MIS-C and bacterial infection in comparison with viral infection and KD." (PMID 39300098, 2024).
breast carcinoma (12 papers, 2010 to 2025). "Furthermore, a recent analysis identified silencing LTF mediated breast cancer cell lines susceptibility." (PMID 40988744, 2025). "Previous reports have demonstrated that LTF downregulation refers to a poor 5-year survival rate in breast cancer patients and correlates with the biochemical recurrence in the hormone-resistant prostate cancer patients receiving radical prostatectomy." (PMID 34944711, 2021). "Lactotransferrin (LTF) has been reported to show disparate expression among AA and CA breast cancer patients." (PMID 32824813, 2020). "TUBB2A was upregulated in more invasive breast cancer cell lines (i.e., BC cell lines in the higher invasive group), whereas the expression patterns of LTF were perturbed across breast cancer cell lines by RT-PCR." (PMID 32489334, 2020). "The difference in the expression of TUBB2A and LTF was validated by RT-PCR in 1 normal breast cell line and 13 breast cancer cell lines, the relative invasiveness of which was determined per other studies." (PMID 32489334, 2020). "LTF expression in breast cancer correlates with the life expectancy of patients and important clinical and physiologic features of the disease." (PMID 32244557, 2020). "Although LTF is mainly found in breast milk, it seems to be that LTF downregulation likely tends to promote cancer progression in female patients with ccRCC and breast cancer." (PMID 32244557, 2020). "Among the hubs of the 6 modules, 5 of them (PTPN22, BRIP1, CEACAM6, LTF, and CCNT1) have been previously found to be associated with breast cancer, and the other one, MXRA5, has been reported to be related to non-small cell lung cancer." (PMID 30240439, 2018). "We observed over-expression of LIMCH1, a gene encoding zinc-binding protein, and also four genes encoding iron-binding proteins (LTF, SLC40A1, CYP4Z1 and CYP4Z2P) previously linked to breast cancer." (PMID 21209903, 2010). "Several of these genes have been linked to breast cancer (MAPT, HMGCS2, NR2F2, TFAP2B, NTN4, SEC14L2 and LTF)." (PMID 21209903, 2010). "LTF might be an auxiliary protein that helps breast cancer cells survive during movement toward distal sites by disrupting the immune system." (PMID 32489334, 2020). "Additionally, gene expression of LTF has previously been shown to correlate with tumor size and survival in breast cancer." (PMID 31356589, 2019). "Immune‐related proteins osteopontin, lactotransferrin, calreticulin, and peroxiredoxin 2 were selected as potential biomarkers of MDSC‐producing breast cancer." (PMID 39939411, 2025). "Based on the criteria, LTF and TUBB2A were selected as important protein targets for validation of their function in relation to distant metastasis of breast cancer." (PMID 32489334, 2020). "Only in glioblastoma the level of LTF is significantly increased compared with normal samples in both TIMER and GEPIA (B red names), while the LTF expression is significantly decreased in breast cancer, gastric cancer and thyroid cancer (B green names)." (PMID 38763993, 2024).
Obesity (8 papers, 2019 to 2025). Accumulation of substantial excess body fat. "The effects of obesity were partly mediated by the differential methylation of LTF and DUSP22." (PMID 32075680, 2020). "Thereby, decreased levels of GHP, TNFRSF11B, and LTF in obesity could facilitate the pathologic development of TC." (PMID 33240576, 2020). "Five out of the 358 obesity-specific genes, FABP4, CFD, GHR, TNFRSF11B, and LTF, presented significantly decreased expression in TC patients (LFC<−1.44; and p-value < 1e−7)." (PMID 33240576, 2020). "Using the system biology approach, we mined a set of genes influenced by obesity to uncover five genes (FABP4, CFD, GHR, TNFRSF11B, and LTF) as previously unrecognized contributors to the development of TC." (PMID 33240576, 2020). "DNA methylation of genes identified such as SLC2A9, HOOK2, LTF, and DUSP22 all have direct or indirect links to diabetes or obesity including immune or inflammatory regulatory pathways, signaling pathways, and clinical disorders related to diabetes and obesity." (PMID 32075680, 2020).
clear cell renal cell carcinoma (7 papers, 2020 to 2024). "Chiu and others demonstrated that primary tumours of clear cell renal cell carcinoma in women characterized by the downregulation of LTF had higher pathologic stages." (PMID 36551770, 2022).
dental caries (7 papers, 2010 to 2025). The decay of a tooth, in which it becomes softened, discolored, and/or porous. "This study highlights a statistically significant association between the LTF gene polymorphism and dental caries susceptibility in a pediatric Saudi population." (PMID 40255521, 2025). "Based on this evidence, the present study aimed to investigate the association between a specific A/G SNP in the LTF gene and dental caries risk in pediatric patients attending the dental department at King Abdulaziz University (KAU), Jeddah, Saudi Arabia." (PMID 40255521, 2025). "Polymorphisms in the LTF gene have been implicated in oral and systemic diseases, but limited data are available regarding their association with dental caries." (PMID 40255521, 2025). "LTF gene polymorphisms have been described and associated with aggressive periodontitis, herpes simplex keratitis, and dental caries." (PMID 22190933, 2011). "The objective of this study was firstly to search the promoter region of the human LTF gene for variations and, if existent, to investigate the association of the identified polymorphisms with dental caries in 12-year-old students." (PMID 22190933, 2011). "Lactotransferrin A/G (exon 2, Lys/Arg) polymorphism was associated with susceptibilityto dental caries in 12-year-old students." (PMID 20485928, 2010). "Thus, we can exclude LTF rs1126478 polymorphism as a risk factor for dental caries; however, more accurate confirmation of results requires further research through larger studies on different ethnicities." (PMID 32375748, 2020). "Thus, the aimof this study was to investigate the association between the polymorphism A/G (Lys/Arg)in the LTF gene and dental caries in 12-year-old students." (PMID 20485928, 2010). "The purpose of this study was to characterize the putative promoter region of LTF gene aiming to identify variations which could affect LTF expression and biological functions, such as iron-binding and bacteria-killing abilities, which could be associated with dental caries." (PMID 22190933, 2011). "Other strongly associated proteins in this pathway were salivary proteins involved in periodontitis (OR=118.80, adjusted, p=0.007; genes: LYZ, LTF) and proteins involved in dental caries (OR=59.36, p=0.007; genes: LYZ, CCL28)." (PMID 41552085, 2025). "Co-expression analysis revealed enrichment in immune and oral health-associated pathways, including salivary protein's role in periodontitis (p=0.007; OR=118.8; LYZ, LTF) and dental caries (p=0.007; OR=59.36; LYZ, CCL28)." (PMID 41552085, 2025). "This meta-analysis evaluated the association of LTF, ENAM, and AMELX polymorphisms with dental caries susceptibility." (PMID 32375748, 2020). "Three prevalent genes are reportedly involved in development of dental caries namely the lactotransferrin (LTF), enamelin (ENAM), and amelogenin X (AMELX)." (PMID 32375748, 2020). "The association between the mutations of LTF, ENAM, and AMELX genes and dental caries susceptibility has been shown in some studies." (PMID 32375748, 2020). "This meta-analysis assessed the association between the common polymorphisms of LTF, ENAM, and AMELX and the risk of dental caries." (PMID 32375748, 2020). "The present study evaluated the association between lactotransferrin (LTF) genepolymorphism (exon 2, A/G, Lys/Arg) and dental caries." (PMID 20485928, 2010). "Among these pathways, key pathways relevant to our hypothesis include the role of salivary proteins in periodontitis (OR=118.80, adjusted, p=0.007; genes: LYZ, LTF) and proteins involved in dental caries (OR=59.36, p=0.007; genes: LYZ, CCL28)." (PMID 41552085, 2025). "However, few studies have explored the direct effects of lactotransferrin-derived peptides on cariogenic bacteria and dental caries." (PMID 34234894, 2021).
dental caries (continued). "The objective of this study was firstly to search the promoter region of the human lactotransferrin gene (LTF) for gene variations and, if existent, to investigate the association of the identified LTF gene polymorphisms in this region with dental caries in 12-year-old students." (PMID 22190933, 2011). "In addition to the antibacterial function, LTF is also involved in various physiological functions, such as iron absorption and modulated immune responses, thereby affecting the development of dental caries." (PMID 32460726, 2020). "However, to the authors' knowledge, there is only one report investigating the association between polymorphisms in LTF gene and dental caries, and there is no study investigating the association of polymorphisms in the promoter region of LTF gene with caries." (PMID 22190933, 2011). "Lactotransferrin (LTF) is an important iron-binding glycoprotein produced by saliva, and it can affect the occurrence and development of dental caries in a variety of ways." (PMID 32460726, 2020).